XPC (XPC complex subunit, DNA damage recognition and repair factor)
Diseases named in the same sentence as XPC in open-access papers (continued):
Sharing a sentence is not in itself a finding about the gene and the disease.
lung adenocarcinoma (10 papers, 2007 to 2025). A carcinoma that arises from the lung and is characterized by the presence of malignant glandular epithelial cells. "The clinical relevance of NER deficiency is supported by studies demonstrating that XPC-KO mice exhibit 2.0-fold increased susceptibility to CS-carcinogen–driven lung adenocarcinomas compared with WT controls." (PMID 40157540, 2025). "Previous studies, including our own, have implicated oxidative stress in the development of lung adenocarcinomas in XPC-deficient mice." (PMID 38672576, 2024). "The high level of XPC in cancer was associated with a better prognosis (Log-rank p = 0.0577) in lung adenocarcinoma patients." (PMID 34803670, 2021). "Our laboratory previously discovered that preventative antioxidant treatment could mitigate lung adenocarcinoma development in XPC deficient mice, suggesting an important role of XPC regulation of BER in lung adenocarcinoma development, also suggested by others." (PMID 38672576, 2024). "The ratio of XPC mRNA expression was decreased in lung adenocarcinoma tissue compared to subject-matched benign lung irrespective of cigarette smoking status and stage at the time of diagnosis." (PMID 40391767, 2025). "We found a significant decrease in XPC gene expression in lung adenocarcinomas compared to unmatched benign lung samples." (PMID 40060594, 2025). "Gene expression data from the TCGA database was used to determine XPC mRNA expression in 502 lung adenocarcinoma samples and 59 benign lung samples." (PMID 40060594, 2025). "Decreased XPC mRNA expression has been identified in human specimens from lung adenocarcinoma and lung squamous cell carcinoma, the two most common NSCLC histologic subtypes." (PMID 35530314, 2022). "In lung adenocarcinoma patients, the expression of XPC was positively correlated with the prognosis, and the expression of CD133 was negatively correlated with the prognosis of the patients." (PMID 34803670, 2021). "And the immunohistochemical results of cancer tissues of 140 patients with lung adenocarcinoma showed that the expression of XPC and CD133 was negatively correlated (p < 0.0006, R = −0.2580)." (PMID 34803670, 2021). "The results showed that XPC is located in the cell nucleus and is highly expressed in lung adenocarcinoma paracancerous tissue while low in cancer tissue (p = 0.0344)." (PMID 34803670, 2021). "The miR-346 has been shown to be involved in proliferation, invasion, and drug resistance of lung adenocarcinoma by positively regulating the XPC/ERK/Snail/E-cadherin pathway." (PMID 29383112, 2017). "The NER factor XPC expression was reported to increase cisplatin resistance in lung adenocarcinoma cells and predict poor prognosis." (PMID 26156020, 2015). "We therefore hypothesized that XPC mRNA would be decrease in lung squamous cell carcinoma compared to normal lung tissue similar to that observed in lung adenocarcinoma." (PMID 40391767, 2025). "We therefore hypothesized that XPC mRNA would be decreased in lung squamous cell carcinoma compared to normal lung tissue similar to that observed in lung adenocarcinoma." (PMID 40060594, 2025). "We found that XPC protects against carcinogen-induced lung adenocarcinoma in mice." (PMID 40060594, 2025). "We and others have shown a protective role of the DNA repair protein xeroderma pigmentosum group C (XPC) in lung adenocarcinoma development, likely through alterations in both global genomic-nucleotide excision repair (GG-NER) and repair of oxidative DNA damage through base excision repair (BER)." (PMID 38672576, 2024). "Mice deficient in the DNA repair protein, Xeroderma Pigmentosum Group C (XPC), are particularly prone to urethane- induced lung adenocarcinoma and develop a range of histologically progressive lesions characteristic of human AAH to lung adenocarcinomas, often synchronously within the same mouse." (PMID 34769463, 2021).
lung adenocarcinoma (continued). "To determine the relationship between the expression of XPC and CD133 and the prognosis of lung adenocarcinoma patients, we obtained the OS of 140 enrolled lung adenocarcinoma patients through telephone follow-up and medical records." (PMID 34803670, 2021). "The 140 lung adenocarcinoma tissues were divided into four groups based on the expression of XPC and CD133 as XPC+CD133−, XPC−CD133−, XPC+CD133+, XPC−CD133+." (PMID 34803670, 2021). "Although the number of normal lung tissue was low for current and never cigarette smoking, XPC gene expression was significantly decreased in lung adenocarcinomas compared to normal lung irrespective of cigarette smoking status and gender (data not shown)." (PMID 40060594, 2025). "Both lung adenocarcinoma and squamous cell carcinoma exhibit decreased XPC mRNA expression compared to non-cancerous adjacent lung tissue removed during surgery from the same subject." (PMID 40060594, 2025). "Median XPC mRNA expression was decreased in human lung adenocarcinoma compared to non-cancerous, resected lung from the same individual." (PMID 40391767, 2025). "While ad-lib access to NAC significantly decreased lung adenocarcinoma development in mice exposed to the carcinogen urethane in our previous study, NAC did not prevent LUSC development in either XPC proficient or deficient mice in the current model." (PMID 38672576, 2024). "Furthermore, the expression of XPC and CD133 is correlated with the prognosis of lung adenocarcinoma." (PMID 34803670, 2021). "To account for this “field effect” and to reduce the potential bias introduced by evaluating gene expression across different individuals, we determined XPC mRNA expression in frozen human lung adenocarcinoma compared to subject-matched non-cancerous adjacent lung from 44 subjects." (PMID 40060594, 2025). "Urethane-treated Xpc-/- mice developed an increase in lung adenocarcinomas compared to their wild-type counterparts, but treatment with the anti-oxidant N-acetylcysteine (NAC) decreased tumor development, further supporting a link between XPC, oxidative damage and cancer development." (PMID 35530314, 2022).
leukemia (9 papers, 2017 to 2026). A malignant (clonal) hematologic disorder, involving hematopoietic stem cells and characterized by the presence of primitive or atypical myeloid or lymphoid cells in the bone marrow and the blood. "A Tunisian study on the analysis of the link between the NER DNA repair genes polymorphisms and susceptibility to leukemia in the Tunisian population found that XPC polymorphism may be involved in the susceptibility to AML." (PMID 34446105, 2021). "The association of variant homozygous genotypes of XPC 939 Gln/Gln and XPG 1104 His/His polymorphisms led to significant interaction with the risk of leukemia, especially in the case of CML (OR = 22.52; 95% CI = 5.38–94.25." (PMID 38541232, 2024). "Indeed, we found a strong replicational bias (average 1.38-fold of all six mutational classes in XP-C leukemia, Wilcoxon signed-rank test, two-sided, P = 2.91e−11) compatible with preferential bypass of purine DNA lesions by error-prone TLS polymerases on the lagging strand in XPC-deficient tumors." (PMID 33203900, 2020).
prostate carcinoma (9 papers, 2015 to 2023). A carcinoma that arises from epithelial cells of the prostate gland. "Prostate cancer (PC) is the most common malignancy in males, and XPC polymorphisms have been correlated to an increased risk of PC development in several studies." (PMID 35530314, 2022). "The Gleason grade categorises patients with prostate cancer based on cell differentiation; the XPC PAT I/I genotype displayed a 2.8-fold increased risk of a high Gleason grade (Adjusted OR-2.88, 95% CI 1.22–6.79, p = 0.015)." (PMID 34884434, 2021). "Numerous studies have assessed the association between xeroderma pigmentosum complementation group C (XPC) polymorphisms and susceptibility of prostate cancer (PCa); however, the findings remain inconsistent." (PMID 32488882, 2020). "We found a significant association between rs1870134 G>C variant genotypes of XPC and a decreased risk of prostate cancer under a dominant genetic model in an Eastern Chinese population for the first time." (PMID 27974699, 2017). "Similarly, the XPC exon 15 variant CC genotype showed a 2.1-fold increased risk of prostate cancer (Adjusted OR- 2.15, 95% CI-1.09–4.23, p = 0.026)." (PMID 34884434, 2021). "In contrast, other XPC polymorphisms, including those heterozygous for Lys939Gln (939Lys/Gln) along with the PAT D/D haplotype are considered protective of prostate cancer." (PMID 35530314, 2022). "For instance, the XPC polymorphism, XPC PAT (PAT I/I genotype) was associated with an increased odds of prostate cancer, associated with a 3.83-fold increased risk in a Tunisian population." (PMID 35530314, 2022). "The expression of XPC was down‐regulated in all Gleason scores of prostate cancer." (PMID 32488882, 2020). "It showed evidence that XPC expression was down‐regulated in all Gleason scores of prostate cancer." (PMID 32488882, 2020). "In prostate cancer, USP22 mediates the deubiquitination of xeroderma pigmentosum complementation group C (XPC), a nucleotide excision repair protein that detects DNA damage." (PMID 34112237, 2021). "Results from TCGA samples indicated a significant correlation between XPC and AKAP10 in prostate cancer." (PMID 32488882, 2020). "Western blot analyses confirmed that miR-890 transfection also reduced the predicted target genes WEE1, XPC and KU80 in LNCaP prostate cancer cells." (PMID 25845598, 2015). "There is a significant correlation between XPC and AKAP10 in prostate cancer." (PMID 32488882, 2020).
xeroderma pigmentosum group C (9 papers, 2012 to 2025). An autosomal recessive inherited disorder caused by mutations in the XPC gene. "In a recent study and in an attempt to elucidate the mutation spectrum of the XPC gene in the Tunisian population, the authors prioritized the screening of the p.V548AfsX25 mutation in 20 Tunisian XP group C patients." (PMID 22908982, 2012). "Xeroderma Pigmentosum group C (XP-C) is an autosomal recessive disorder caused by mutations in the XPC gene, leading to defective nucleotide excision repair." (PMID 41440007, 2025).
squamous cell carcinoma (8 papers, 2007 to 2025). A carcinoma arising from squamous epithelial cells. "Lung squamous cell carcinomas occur almost exclusively in those with a cigarette smoking history; both current and former cigarette smoking was associated with decreased XPC gene expression in squamous cell carcinoma compared to normal lung tissue." (PMID 40060594, 2025). "The association of XPC rs2229090 was more apparent in adenocarcinoma than in squamous cell carcinoma patients." (PMID 28878296, 2017). "Although XPC rs2229090 GC/CC genotypes were significantly associated with PFS in squamous cell carcinoma patients who received docetaxel-cisplatin, the sample size of this treatment group was relatively small (n = 56); hence, this result needs to be interpreted with caution." (PMID 28878296, 2017). "Additionally, XPC deficiency in mice exposed to the carcinogen N-nitroso-tris-chloroethylurea (NTCU) is associated with an increased frequency and size of lung squamous cell carcinomas and earlier progression of pre-malignant squamous dysplasia." (PMID 40391767, 2025). "In squamous cell carcinoma (SCC), as the rs2228000, rs2228001 (XPC), rs2273953 (TP73), rs2279744 (MDM2), rs2299939 (PTEN) and rs8178085, rs12334811 (DNA-PKcs) affected the sensitivity to chemotherapy, so did the rs8178085, rs12334811 to radiotherapy." (PMID 27246533, 2016). "Using archived gene expression data from 501 squamous cell carcinomas and 51 non-cancerous lung specimens stored in the TCGA database, we observed decreased XPC mRNA expression in lung squamous cell carcinoma compared to normal lung samples." (PMID 40060594, 2025). "XPC PAT+/+ genotype was associated with no statistically significant increased risk among ever smokers (OR = 1.40; 95%CI = 0.94–2.08), squamous cell carcinoma (OR = 1.44; 95%CI = 0.85–2.44), and adenocarcinoma (OR = 1.72; 95%CI = 0.97–3.04)." (PMID 17705814, 2007).
non-small cell lung carcinoma (7 papers, 2007 to 2025). A group of at least three distinct histological types of lung cancer, including non-small cell squamous cell carcinoma, adenocarcinoma, and large cell carcinoma. "Further translational and mechanistic studies are needed to investigate the epigenetic causes of decreased XPC gene expression in non-small cell lung cancer tumors compared to adjacent lung tissue." (PMID 40060594, 2025). "This study provides insights into the potential mechanistic role of XPC-mediated DNA repair in the development of both non-small cell lung cancer and emphysema." (PMID 40060594, 2025). "Deletion of XPC is associated with early stages of human lung carcinogenesis, and reduced XPC mRNA levels predict poor patient outcome for non-small cell lung cancer (NSCLC)." (PMID 25871391, 2015). "Non-small cell lung cancer cell lines (A549, H1299 and H520) were modified by stable XPC knock-down (shXPC) or non-targeted control (shCtrl) as published." (PMID 40391767, 2025).
lung squamous cell carcinoma (5 papers, 2016 to 2025). "For this reason, we evaluated XPC mRNA expression by RT-qPCR in frozen lung squamous cell carcinoma and matched resected lung specimens from 36 subjects." (PMID 40060594, 2025). "XPC gene expression is frequently decreased in the early stages of human lung squamous cell carcinoma and adenocarcinoma." (PMID 40060594, 2025). "Here, we show the critical role of the DNA repair protein, Xeroderma Pigmentosum Group C (XPC), in protecting against the development and histologic progression of lung squamous cell carcinoma (LUSC)." (PMID 38672576, 2024). "In conclusion, our study underscores the protective role of XPC in averting the onset of lung squamous cell carcinoma." (PMID 38672576, 2024). "Little is known about the role of XPC in lung squamous cell carcinoma (LUSC) development." (PMID 40060594, 2025). "We hypothesized that XPC would protect against lung squamous cell carcinoma development and progression and tested this using a mouse model of carcinogen-induced lung squamous cell carcinoma." (PMID 38672576, 2024). "Importantly, lung squamous cell carcinomas had decreased XPC gene expression ratio compared to subject-matched adjacent, non-cancerous lung, further confirming that observed decreases in XPC in NSCLCs is tumor-related rather than due to inter-individual changes." (PMID 40060594, 2025). "The results showed that the SNPs in XPC (rs2228000 and rs2228001), TP73 (rs2273953), MDM2 (rs2279744), PTEN (rs2299939) and DNA-PKcs (rs8178085 and rs12334811) genes significantly affected the sensitivity of lung squamous cell carcinoma to chemotherapy." (PMID 27246533, 2016). "Additionally we found that the rs2228001 (XPC) and rs2228000 (XPC) were related with the sensitivity of chemotherapy and rs344781 (PLAUR) was related with the survival of patients of lung squamous cell carcinoma by eQTLs analysis." (PMID 27246533, 2016).
osteosarcoma (5 papers, 2013 to 2023). A usually aggressive malignant bone-forming mesenchymal neoplasm, predominantly affecting adolescents and young adults. "One of these tumors also contained a prevalent missense mutation in XPC, p.Q939K, which has been reported to affect the response to cisplatin in patients with osteosarcoma." (PMID 32300177, 2020). "The XPC c.2815AA genotype was associated with an increased risk of any grade of toxicity in a previous analysis of the data conducted by our group, and the same effect was observed in a smaller subset of patients with osteosarcoma." (PMID 36980643, 2023). "Indeed, XPC gene of the nucleotide excision repair pathway (NER) was associated with ototoxicity in children and young adults treated for osteosarcoma." (PMID 27618021, 2016). "Therefore, in our study, we aimed to assess the role of XPG, XPC, CCNH and MMS19L polymorphisms response to chemotherapy in osteosarcoma." (PMID 24353725, 2013).
Age-related cataract (4 papers, 2016 to 2021). A type of cataract (opacification of the lens) that forms during the course of aging. "They found that an allele in the 3′ UTR of the XPC gene differed in luciferase reporter gene expression and was linked to an increased risk of nuclear type of age-related cataracts." (PMID 34026885, 2021). "Polymorphism genotype distribution (rs 2228000) in XPC gene in pre-senile and senile cataracts groups." (PMID 27248495, 2016). "Polymorphism genotype distribution (rs 2228000) in XPC gene in pre-senile cataracts group and the group with no cataract." (PMID 27248495, 2016). "Polymorphism genotype distribution (rs 2228000) in XPC gene in the senile cataracts group and the group with no cataract." (PMID 27248495, 2016).
bladder tumors (4 papers, 2011 to 2021). "Nearly 42% (15/36) of the bladder tumors expressed at least two-fold lower levels of XPC protein than co-cultured fibroblasts (0–50%)." (PMID 25927440, 2015). "Furthermore, it was shown that attenuated expression of the NER protein XPC is present in ~40% of all bladder tumors and a contributing factor in tumor progression." (PMID 25927440, 2015). "Because of the essential role of the XPC protein in initiating DNA damage-induced cellular responses, these results further suggest that silencing of the XPC gene may provide a critical early event for initiation of bladder tumors." (PMID 21507255, 2011). "We established a reproducible method to obtain a short-term single layer cell culture from fresh bladder tumor specimens to perform our assays and conclude that low XPC expression not necessarily results in defective NER." (PMID 25927440, 2015). "Therefore, we measured the XPC protein expression level and functional NER activity of 36 bladder tumors in a standardized manner." (PMID 25927440, 2015). "We conclude that XPC protein levels should not be used as a biomarker to select bladder tumors for impaired DNA repair capacity." (PMID 25927440, 2015). "We then sought to address whether the XPC PAT −/+ and the XRCC3Thr241Met SNPs follow any particular phenotypical pattern with respect to patients’ histopathological characteristics, including grade, stage, recurrent disease, and number and diameter of bladder tumors." (PMID 34068981, 2021).
Cockayne syndrome (4 papers, 2015 to 2024). A multisystem condition characterized by short stature, a characteristic facial appearance, premature aging, photosensitivity, progressive neurological dysfunction, and intellectual deficit. "TCR‐NER requires Cockayne syndrome group A and Cockayne syndrome group B to detect the lesion, while in GGR‐NER, the XPC and DNA damage‐binding protein B2 (DDB2) participate in the process." (PMID 39492835, 2024). "This is directly attributable to causative disease mutations being present in GGR genes, XPC and DDB2 (XPE) in patients with XP, but not in the transcription coupled repair (TCR) genes CSA and CSB in Cockayne’s syndrome." (PMID 26913219, 2015).